CRNDE (colorectal neoplasia differentially expressed)
Diseases named in the same sentence as CRNDE in open-access papers (continued):
Sharing a sentence is not in itself a finding about the gene and the disease.
gastric cancer (6 papers, 2020 to 2025). A primary or metastatic malignant neoplasm involving the stomach. "Recent studies have identified several lncRNAs, HOXA transcript at the distal tip (HOTTIP), FGD5-AS1 and CRNDE, as being upregulated in cisplatin-resistant gastric cancer cells." (PMID 40781643, 2025). "A previous study has shown that CRNDE is highly expressed in gastric cancer (GC) cell lines and tissues and CRNDE overexpression promotes cell proliferation." (PMID 32426817, 2020). "In gastric cancer (GC), lncRNA CRNDE directly binds to splicing protein SRSF6 to reduce its protein stability, which in turn reduces PICALM alternative splicing, triggering a significant switch from the short to long isoform to induce attenuated chemoresistance." (PMID 39937018, 2025). "Another lncRNA, CRNDE, is also found to be upregulated in cisplatin-resistant gastric cancer." (PMID 40781643, 2025). "Another study showed that the expression of CRNDE in GC was not different between gastric cancer and normal tissues both in the TCGA database or GEO database, and it was not related to the OS of patients with GC 31, which is consistent with our results." (PMID 36046639, 2022).
colon cancer (4 papers, 2017 to 2024). "For example, CRNDE ranked the top 5 up-regulated lncRNAs in our study, and previous studies suggest that CRNDE overexpression in colon cancer cells promotes cell growth and chemoresistance of colon cancer cells by medicating Wnt/ß-catenin activation." (PMID 34229645, 2021). "In recent years, CRNDE has been confirmed as up-regulated within colon cancer and has promoted the development of other tumors." (PMID 34863152, 2021). "As a result, the associations between colon cancer and HOTAIR, CRNDE, and MALAT1 (top 3 predictions) were verified by the updates in the LncRNADisease database." (PMID 28963512, 2017). "CRNDE is highly expressed in colorectal adenomas and colon cancer and may play a role through PI3K signaling in other cancers." (PMID 38609520, 2024).
colorectal adenoma (3 papers, 2021 to 2024). An adenoma that arises from the colon or rectum. "The expression of the CRNDE gene is increased in proliferating tissues and is involved in the expression of genes associated with metabolism and in neoplasms such as colorectal adenomas and adenocarcinomas." (PMID 38435839, 2024).
glioblastoma (3 papers, 2020 to 2022). The most malignant astrocytic tumor (WHO grade IV). "Lower FREM2 expression and overexpression of CRNDE (Colorectal Neoplasia Differentially Expressed) non-coding RNA are associated with worse prognosis for glioblastoma patients." (PMID 36613601, 2022). "This was the gene for noncoding RNA CRNDE (ColoRectal Neoplasia Differentially Expressed) that was previously associated with many cancers including glioblastoma." (PMID 34298634, 2021). "In addition, growing evidence indicates that lncRNAs have various roles in resistance to glioblastoma therapies (e.g., MALAT1, H19) and in glioblastoma progression (e.g., CRNDE, HOTAIRM1, ASLNC22381, ASLNC20819)." (PMID 32650527, 2020).
lung carcinoma (3 papers, 2017 to 2023). "The latest reports indicate some lncRNAs, such as PCGEMI, UCA1, lincRNA-p21 and CRNDE play a positive role in cancer cell glucose metabolism to contribute to the Warburg effect, however, it remains largely unknown whether and how lncRNA regulates cellular energy metabolism in lung cancer." (PMID 28946875, 2017).
ovarian carcinoma (3 papers, 2015 to 2024). A malignant neoplasm originating from the surface ovarian epithelium. "In accordance to these findings, we also identified CRNDE as a novel molecular marker of poor prognosis in ovarian cancer." (PMID 25978564, 2015). "Moreover, in borderline ovarian tumors (BOTS), but not in ovarian cancers, the presence of a single nucleotide polymorphism in CRNDE, rs115515594, significantly increased the risk of recurrence." (PMID 39062774, 2024).
renal cell carcinoma (3 papers, 2019 to 2023). "CRNDE is found to be overexpressed in colorectal adenomas and adenocarcinomas, and several other cancers, such as NSCLC, HCC, GC, OC, renal cell carcinoma (RCC), and glioma." (PMID 31480503, 2019).
asthma (2 papers, 2022 to 2023). "We first checked the levels of lncRNA CRNDE in a mouse model of asthma and found the level in the model group to be significantly higher than that in the control group." (PMID 36743692, 2023). "In support of the role of CRNDE in airway remodeling in asthma, neutrophil CRNDE knockdown in a mouse model of asthma induced by ovalbumin reduced both hyperplasia and hypertrophy, reducing the thickness of the bronchial smooth muscle layer." (PMID 36291183, 2022).
cervical cancer (2 papers, 2023). A primary or metastatic malignant neoplasm involving the cervix. "According to extensive studies, lncRNA CRNDE also serves as an essential role in ovarian and cervical cancers." (PMID 37934582, 2023). "LncRNAs MEG3, CRNDE, LINP1 and SNHG20 are shown to influence cervical cancer progression and we report G4 specific protein partners for these lncRNAs." (PMID 37628839, 2023).
gallbladder carcinoma (2 papers, 2017). "Apart from functional role of CRNDE as a competitive endogenous RNA, CRNDE also played the oncogenic role via acting a scaffold of DMBT1 and C-IAP1 complexes to activating PI3K-AKT pathway in gallbladder cancer." (PMID 29299168, 2017).
leukemia (2 papers, 2012 to 2019). A malignant (clonal) hematologic disorder, involving hematopoietic stem cells and characterized by the presence of primitive or atypical myeloid or lymphoid cells in the bone marrow and the blood. "CRNDE expression is up-regulated in many solid tumors and leukemias, and is associated with a stemness signature." (PMID 31489115, 2019).
medulloblastoma (2 papers, 2023 to 2024). A malignant, invasive embryonal neoplasm arising from the cerebellum. "HOTAIR, NEAT1, linc-NeD125, HHIP-AS1, CRNDE, and TP73-AS1 are the oncogenic lncRNAs, and Nkx2-2as is a tumor-suppressive lncRNA that develop lncRNA-associated ceRNA networks in medulloblastoma." (PMID 39010056, 2024). "Overall, the current evidence indicates that HOTAIR, NEAT1, linc-NeD125, HHIP-AS1, CRNDE, and TP73-AS1 are oncogenic lncRNAs and Nkx2-2as is a tumor-suppressive lncRNA that forms lncRNA-associated ceRNAs in medulloblastoma." (PMID 39010056, 2024). "HOTAIR, NEAT1, linc-NeD125, HHIP-AS1, CRNDE, and TP73-AS1 are the identified oncogenic lncRNA in medulloblastoma, and Nkx2-2as is a tumor-suppressive lncRNA in medulloblastoma." (PMID 39010056, 2024). "For instance, NKX2-2AS has been shown to suppress tumorigenesis in SHH-driven medulloblastoma, while HHIP-AS1, TP73-AS1, CCAT1, CRNDE, LOXL1-AS1, ANRIL, and linc-NeD125 have been reported to promote medulloblastoma cell proliferation and migration." (PMID 37976029, 2023).
acute monocytic leukemia (1 paper, 2022). Acute monoblastic leukemia (AML-M5), is one of the most common subtypes of acute myeloid leukemia (AML) that is either comprised of more than 80% of monoblasts (AML-M5a) or 30-80% monoblasts with (pro)monocytic differentiation (AML-M5b). "Finally, we verified the expression levels of CRNDE, CHROMR and NARF-IT1 in ML cell lines K562, MOLM13 and acute monocytic leukemia cell line THP-1, which were significant." (PMID 34996458, 2022).
chronic lymphocytic leukemia (1 paper, 2024). "On the other hand, in chronic lymphocytic leukemia (CLL), CRNDE regulates the expression of NDRG2 through miR-28, where it suppresses the proliferation and stimulates apoptosis of MEG1 and HG3 cells." (PMID 39335585, 2024).
colorectal adenocarcinoma (1 paper, 2015). The most common type of colorectal carcinoma. "In accordance with our results, other researchers reported CRNDE overexpression in more than 90% of colorectal adenocarcinomas." (PMID 26556866, 2015).
diabetes (1 paper, 2019). "While the mechanism of CRNDE’s action in endothelial cells is unknown, CRNDE has the potential to be a novel target in the fight against the angiogenic complications of diabetes and obesity." (PMID 31863035, 2019).
hepatoblastoma (1 paper, 2017). Hepatoblastoma (HB) is a malignant hepatic tumor and is the most common pediatric liver cancer. "Taken together, these results suggest that CRNDE is a potential regulator of hepatoblastoma development and tumor angiogenesis." (PMID 28178668, 2017). "In this study, we show that CRNDE knockdown inhibits tumor growth and tumor angiogenesis in vivo, and reduces hepatoblastoma cell viability and angiogenic effect in vitro." (PMID 28178668, 2017). "CRNDE up-regulation contributes to the development of hepatoblastoma." (PMID 28178668, 2017). "Here we put the spotlight on the function of CRNDE, a lncRNA up-regulated in hepatoblastoma." (PMID 28178668, 2017). "CRNDE is up-regulated during the development of hepatoblastoma." (PMID 28178668, 2017). "Moreover, inhibition of mTOR signaling could inhibit CRNDE overexpression-induced up-regulation of hepatoblastoma cell viability and abnormal angiogenic effect." (PMID 28178668, 2017). "We speculated that CRNDE is also shown as an oncogene in hepatoblastoma." (PMID 28178668, 2017).
liver cancer (1 paper, 2021). An epithelial or non-epithelial malignant neoplasm that arises from the liver. "The expression of CRNDE is up‐regulated in human liver cancer tissues and is also associated with clinical staging and lymph node metastasis." (PMID 33742511, 2021). "By using RNA sequencing technology to analyse the expression of lncRNA, Esposti found that the expression of CRNDE was up‐regulated, which could be used as a potential diagnostic marker for the prognosis of liver cancer." (PMID 33742511, 2021).
melanoma (1 paper, 2019). A malignant, usually aggressive tumor composed of atypical, neoplastic melanocytes. "Second, previous works have reported some lncRNAs associated with melanoma prognosis, such as DSCAM-AS1, CRNDE, and CACS2, which were not involved in our results." (PMID 31649871, 2019).
mesothelioma (1 paper, 2020). A usually malignant and aggressive neoplasm of the mesothelium which is often associated with exposure to asbestos. "LOC642852 and LOC388796 showed a constant down-regulation in all cell lines, whereas CRNDE and LOC100130776 showed no altered regulation in mesothelioma cell lines." (PMID 32435497, 2020).
ovarian tumors (1 paper, 2024). "A complete coding sequence of the CRNDE gene (NM_001308963) was searched for genetic alterations, potentially affecting the structure and/or function of the CRNDEP micropeptide, in the entire set of 225 ovarian tumors investigated herein." (PMID 39062774, 2024).
papillary thyroid cancer (1 paper, 2017). "Further mechanistic studies highlighted the important roles of CRNDE/miR-384/PTN axis in the progression of PTC, in which CRNDE promotes cell proliferation, invasion and migration at least partly via competitively binding miR-384 in papillary thyroid cancer." (PMID 29299168, 2017).
prediabetes (1 paper, 2023). "In our study, we also identified an intergenic SNP (rs9929651) between IRX3 and CRNDE, as well as multiple SORCS2 SNPs, that showed significant associations with HDL-C levels in individuals with prediabetes." (PMID 38371897, 2023).
rectal cancer (1 paper, 2022). A primary or metastatic malignant neoplasm that affects the rectum. "The expression levels of the onco-lncRNAs, including CCAT1, LOC152578, UCA1, CRNDE, PVT1, MALAT1, XLOC_000303, XLOC_006844, BCAR4, and HOTAIR, were significantly increased in the rectal cancer patients compared to the control group." (PMID 35654932, 2022).
renal carcinoma (1 paper, 2018). A carcinoma arising from the epithelium of the renal parenchyma or the renal pelvis. "It is noteworthy that CRNDE, which appears upregulated in this subtype, has recently been demonstrated to promote renal carcinoma cell proliferation via the WNT/β-catenin pathway." (PMID 29963224, 2018).
rhabdomyosarcoma (1 paper, 2017). A rare aggressive malignant mesenchymal neoplasm arising from skeletal muscle. "MEG3 CRNDE, LINC00340, and RMST (rhabdomyosarcoma 2 associated transcript) is also found in various cancers." (PMID 28321286, 2017).
cancer (47 papers, 2012 to 2026). A tumor composed of atypical neoplastic, often pleomorphic cells that invade other tissues. "During the functional enrichment analysis of these lncRNAs, we found that LINC01221 and CRNDE had the highest number of interactions across various pathways associated with cancer progression." (PMID 38336706, 2024). "It is known that there are 12 alternatively spliced variants of CRNDE, of which CRNDE-g is a highly expressed isoform in multiple cancer types." (PMID 37628839, 2023). "Given the complex repertoire of splice variants of CRNDE, it will be important to identify/characterize in more detail the transcript profile in different cancer types." (PMID 23226159, 2012). "In view of its association with cancer, the high expression of CRNDE in meiotic/postmeiotic sperm cells is noteworthy considering the existence of a “cancer/testis antigen” (CTA) category of genes, a correlation that implies connections between spermatogenesis and somatic tumorigenesis." (PMID 23226159, 2012). "Genes such as FENDRR, MALAT1, FUS, and CRNDE were found to be involved in numerous cancer-stage-cell processes." (PMID 40728857, 2025). "Several key genes, including MALAT1 and CRNDE, were extensively involved in cancer progression and exhibited distinct regulate patterns across various cancers." (PMID 40728857, 2025). "Our findings indicate that several key genes, including MALAT1 and CRNDE, are widely involved in cancer progression and exhibit various patterns in multiple cancers." (PMID 40728857, 2025). "For instance, MALAT1 was involved in 195 synergistic pairs shared across two or more cancers, while CRNDE was involved in 148 such pairs." (PMID 40728857, 2025). "CRNDE is a well-conserved intergenic lncRNA that has previously been shown to be overexpressed in many types of cancer, including RCC35–38." (PMID 39091767, 2024). "Previous studies have shown the association of HOTAIRM1, CRNDE, and TUG1 expression in the pathogenesis of various cancers, including ALL." (PMID 37303492, 2022). "The expression of CRNDE regulates cancer cell proliferation, migration, invasion, and apoptosis through multiple signaling pathways, such as WNT/β-catenin, PI3K/AKT, and mTOR signaling pathways." (PMID 36090045, 2022). "CRNDE is involved in cancer progression, neuronal differentiation, gametogenesis, and other developmental processes." (PMID 36060266, 2022). "Among the lncRNAs in these gene pairs, CRNDE, CHL1-AS2, and TBX5-AS1 have been associated with different types of cancers." (PMID 34003819, 2021). "CRNDE is also found to be overexpressed in various cancers, including, ovarian, pancreatic, liver, kidney, and leukemia." (PMID 33891491, 2021). "The increased expression of PVT1, CYTOR, FOXD2-AS1, and CRNDE were seen in various cancers, similarly these lncRNAs were all up-regulated in G-CIMP-low suggesting their more oncogenic activity leads to poor prognosis compared to G-CIMP-high." (PMID 33926464, 2021). "CRNDE has been identified as an oncogene of various cancers, which is highly expressed in tumor cells and plays a role in regulating cell proliferation, migration, invasion, and apoptosis." (PMID 32399391, 2020). "Sum up, CRNDE facilitates cancer cells invasion and migration by intervening multiple metastasis-related genes, highlighting the important role of CRNDE-mediated regulatory networks in cancer invasion and migration." (PMID 32435153, 2020). "We found that there are higher number of literature for up-regulated PVT1, CCAT1 and CRNDE, suggesting that they have been mostly investigated in cancer." (PMID 32127004, 2020). "As an oncogene, CRNDE has been acknowledged to induce cancer cells proliferation, trigger EMT, promote metastasis and regulate the immune microenvironment." (PMID 32435153, 2020).
cancer (continued). "Growing evidence suggests the oncogenic role of CRNDE is achieved through regulating proliferation, apoptosis, transition, invasion and migration of cancer cells." (PMID 33298855, 2020). "Among lncRNAs displaying expression differences between PN and MES GSCs, we identified six lncRNAs associated with survival in GBM and other cancers: CTD-2589M5.5, MYOSLID, CRNDE, AC005264.2, SOX21-AS1 and RP11-575F12.1." (PMID 31969990, 2020). "Apart from the the oncogenic role of CRNDE in colorectal adenomas and adenocarcinomas, the dysregulations of CRNDE were also found in other types of cancers including liver cancer, gastric cancer, gallbladder carcinoma, breast cancer, glioma." (PMID 29299168, 2017). "Our results included some well-known cancer-associated lncRNAs such as HOTAIR, PCA3, PCAT1, and CRNDE." (PMID 27147563, 2016). "Remarkably, this is the first study investigating a clinical importance of the CRNDE gene in cancer patients." (PMID 26556866, 2015). "Whereas we discovered CRNDE as a gene upregulated in colorectal neoplasia, it is evident that CRNDE expression is increased in a variety of other neoplastic diseases, especially cancers of the blood and brain." (PMID 23226159, 2012). "CRNDE was reported to regulate cell proliferation and apoptosis in cancers." (PMID 38822362, 2024). "While we could not find any other reports about the LINC01221 but the role of CRNDE has been vastly reported in different types of cancer progression." (PMID 38336706, 2024). "The risk signature of our study included 8 lncRNAs (CRNDE, LINC00844, FAM66C, TUBA3FP, SNHG8, HAR1A, LINC00641, and MYCNOS), and previous evidence has suggested that these lncRNAs are closely linked to the occurrence and development of cancer." (PMID 35832170, 2022). "CRNDE has been shown to regulate neuronal differentiation, gametogenesis, and cancer progression." (PMID 33891491, 2021). "An increasing number of studies have shown that CRNDE could act as a competitive endogenous RNA (ceRNA) or molecular sponge to target some certain microRNAs, thus inducing the proliferation of different cancers." (PMID 32435153, 2020). "Moreover, CRNDE was reported to competitive bind with miR-217 and miR-181a-5p, increasing Wnt/β-catenin signaling activity to participate in different cancer cells proliferation." (PMID 32435153, 2020). "Indeed, the results from GEPIA database showed a higher expression of CRNDE in cancer patients than in heathy individuals." (PMID 32826865, 2020). "A large number of articles have identified that lncRNAs such as lncRNA PVT1, lncRNA HULC, and lncRNA CRNDE are closely related to the initiation and progression of various cancers and could serve as prognostic biomarkers." (PMID 32493915, 2020). "In addition, CRNDE participates in diverse cancer biological processes, including proliferation, apoptosis, invasion and metastasis, by regulating multiple target genes and affecting complicated signaling pathways." (PMID 32435153, 2020). "CRNDE acts through epigenetic mechanisms to regulate cell function, which may relate to its deregulation in cancer, such as histone acetylation or methylation." (PMID 28178668, 2017). "Besides cancer progression, the CRNDE gene also participated in the regulation of neuronal differentiation, gametogenesis and other developmental processes." (PMID 28086904, 2017). "The CRNDE gene seems to play an oncogenic role in cancers, though its exact function remains unknown." (PMID 26556866, 2015). "While de-regulated CRNDE expression – and particularly elevated expression – is common to many cancers, we have little understanding of whether its upregulation confers an oncogenic phenotype, as it potentially does in CRC." (PMID 23226159, 2012). "In addition, CRNDE is involved in the initiation and tumorigenesis of several cancers." (PMID 35359593, 2022).